NF1 (neurofibromin 1)
Diseases named in the same sentence as NF1 in open-access papers (continued):
Sharing a sentence is not in itself a finding about the gene and the disease.
glioblastoma (continued). "A study reported that the molecular classification of glioblastoma involving IDH1, PDGFRA, EGFR, and NF1 substantially benefits the prediction of prognosis and response to therapy in glioblastoma patients." (PMID 36090889, 2022). "The efforts for molecularly classifying glioblastoma have been recently reviewed and are based on a bioinformatics study categorizing in three different clusters the tumors with EGFR, NF1, and PDGFRA/IDH genetic alterations." (PMID 34572759, 2021). "Additionally, somatic mutations of MLL2 have been detected in neurofibromatosis 1-glioblastoma (NF1-GBM), leading to the truncation of the MLL2 protein and have been associated with early steps of gliomagenesis." (PMID 34440566, 2021). "These glioblastoma molecular subgroups are classified as G1/EGFR, G2/FGFR3, G3/NF1, G4/RAF, G5/PDGFRA, G6/Multi-RTK, and G7/Other." (PMID 34572759, 2021). "The integrated genomic and transcriptomic analysis of the tumors showed EGFR, PDGFRA, FGFR3, NF1, and BRAF/RAF1 mutually exclusive alterations within the glioblastoma IDH-wild-type category." (PMID 34572759, 2021). "The NF1 and RAF subgroups accounted for almost one-quarter of the glioblastoma IDH-wild-type cases, with the NF1 subgroup being the second largest after the EGFR subgroup." (PMID 34572759, 2021). "Exposure to lysophosphatidic acid (LPA), platelet derived growth factor (PDGF), and EGF was shown to promote NF1 phosphorylation via PKC-α and its ubiquitination and rapid destruction in mouse embryonic fibroblasts and glioblastoma cells." (PMID 33096593, 2020). "In patients, NF-1-deficient tumors exhibit an increased M2-like macrophage signature compared to tumors with normal NF-1 levels, not only amongst IDH-wild type glioblastomas but also specifically in MES tumors." (PMID 31632393, 2019). "The glioblastoma U87 and the schwannoma ST88-14 cell lines were chosen because their NF1 levels are low, meaning that in those cell lines LIMK2 activity is not downregulated by NF1." (PMID 25593987, 2014). "Targeted DNA sequencing identified CDKN2A/B homozygous deletion as a poor prognostic marker in somatic NF1-mutant, but not NF1 wild-type, glioblastoma." (PMID 40985888, 2025). "Here, we combine multiplatform bulk and single-cell genomic analysis of somatic NF1-mutant, IDH wild-type glioblastomas with genome-wide CRISPRi screens and mouse intracranial tumor models to better understand the molecular landscape and MEK inhibitor responses in these tumors." (PMID 40985888, 2025). "Targeted DNA sequencing of somatic NF1-mutant, IDH wild-type glioblastomas identifies CDKN2A/B loss as a negative prognostic factor." (PMID 40985888, 2025). "Integrated transcriptomic studies have revealed shared transcriptional programs between IDH-wildtype glioblastomas and IDH-mutant grade 4 astrocytomas, mediated by transcription factors such as the neurofibromatosis 1 (NF1) family, which play roles in tumour development and maintenance." (PMID 41179304, 2025). "Taken together, our findings identify clinically important subgroups of NF1-mutant, IDH wild-type glioblastomas and delineate mechanisms of MEK inhibitor response, informing the development of synergistic therapies for NF1-mutant glioblastomas." (PMID 40985888, 2025). "Taken together, our analysis reveals NF1-mutant MES-like glioblastoma tumor cells harbor a distinct molecular signature associated with Ras/RAF/MEK activation compared with either non-MES cells or NF1 wild-type glioblastomas." (PMID 40985888, 2025).
glioblastoma (continued). "Given the increased MEK activation observed in MES-like tumor cells from NF1-mutant glioblastomas and the clinical approval of multiple MEK inhibitors for NF1-mutant nervous system tumors, we next sought to functionally evaluate the therapeutic relevance of MEK inhibition." (PMID 40985888, 2025). "Minimal NF1 immunoreactivity is a poor prognostic marker, even in IDH-wildtype glioblastoma without apparent NF1 genomic alterations, but the underlying molecular mechanism requires further investigation." (PMID 39472976, 2024). "Although glioblastomas are not as common in NF1 as other tumors, estimated to account for approximately 7% of cases, they remain a significant consideration within the spectrum of neoplasms associated with the condition." (PMID 39211378, 2024). "Functional loss of ATRX resulted in ALT in U251, but not in SF188, and ALT features were present in the NF1-glioblastoma line JHH-NF1-GBM1 as demonstrated by the c-circle assay and telomere-specific FISH." (PMID 35740680, 2022). "The combined NF1, RAF, and RTK alterations from EGFR, PDGFRA, FGFR3, and Multi-RTK subgroups that activate the ERK/MAPK signaling pathway accounted for 85% of the glioblastoma IDH-wild-type cases." (PMID 34572759, 2021). "In our center we routinely perform DNA methylation profiling of all IDH wild-type diffuse gliomas not showing histological criteria of glioblastoma and of all tumors developing in a tumor syndrome (e.g. NF1)." (PMID 33905054, 2021). "With a lack of glioblastoma samples with quantified NF1 protein available, the trend of less protein present in samples scored as NF1 inactivated by the classifier nevertheless remains promising." (PMID 28166733, 2017). "To further characterize gene expression in the Ad-GSCs and Sp-GSCs tumor xenografts, we examined the expression of genes previously defined to be characteristic of the Classical (FGFR3, PDFA, EGFR, AKT-2 and Nestin) and Mesenchymal (CHI3L1, TRADD, NF1, RelB and CASP4) glioblastoma subtypes." (PMID 25955030, 2015). "Interestingly, both antibodies identified a subset of glioblastoma that was apparently genomically intact for NF1 but demonstrated minimal to absent protein expression—the NFC antibody more so than iNF-07E (18/42 vs. 4/42)." (PMID 39472976, 2024). "U87-MG is recognized as a human glioblastoma cell line of unknown origin and has reduced levels of NF1 due to elevated proteasomal degradation as opposed to possessing an NF1 mutation." (PMID 39016685, 2024). "For example, gene expression signatures in colon adenocarcinoma (COAD) and glioblastoma (GBM) stratified tumors with aberrant KRAS and NF1 function, respectively." (PMID 29617658, 2018). "An NF1 microdeletion in combination with an abnormal karyotype is an indicator of poor prognosis in AML; 7.6% of ovarian serous cystadenocarcinomas, 2.8% of lung squamous cell carcinomas, 3.3% of glioblastomas and 1.9% of phaeochromocytomas/paragangliomas harboured deletions." (PMID 28637487, 2017). "Targeted DNA sequencing of NF1-mutant, IDH wild-type glioblastomas (n = 186) identified CDKN2A/B homozygous deletion as a poor prognostic marker in NF1-mutant, but not NF1 wild-type, glioblastomas." (PMID 40985888, 2025).
glioblastoma (continued). "Here, we evaluated the public literature supporting the role of NF1 as a prognostic biomarker and found that the presence of an alteration does not correlate with survival in IDH-wildtype glioblastoma." (PMID 39472976, 2024).
malignant peripheral nerve sheath tumor (167 papers, 2006 to 2026). Malignant peripheral nerve sheath tumor (MPNST) is a rare and often aggressive soft tissue sarcoma occurring in a wide range of anatomical sites. "Individuals with NF1 have an increased risk of tumors, including malignant peripheral nerve sheath tumors and different types of cancer." (PMID 40764996, 2025). "This has direct clinical implications, supporting earlier diagnosis, tumor surveillance, and management of NF1-associated conditions such as plexiform neurofibromas and malignant peripheral nerve sheath tumors." (PMID 40428382, 2025). "Malignant peripheral nerve sheath tumours are rare, causing 5-10% of all adult soft tissue sarcomas to be related to NF-1, with 25-50% of those cases linked to the condition." (PMID 40230769, 2025). "Patients with microdeletions in the NF1 gene were reported to have a 4-fold increased risk of malignant peripheral nerve sheath tumors (MPNST) and this risk was further increased with codeletion of SUZ12 or EED gene." (PMID 39257551, 2024). "Malignant peripheral nerve sheath tumors are reported to be associated with NF-1 gene mutation, and its incidence in both benign and malignant forms is associated with NF-1 genetic mutation." (PMID 39205702, 2024). "Malignant peripheral nerve sheath tumors (MPNSTs) are aggressive, Ras-driven sarcomas characterized by loss of the NF1 tumor suppressor gene and hyperactivation of MEK and CDK4/6 kinases." (PMID 39347707, 2024). "A malignant peripheral nerve sheath tumor (MPNST) is associated with neurofibromatosis type 1 (NF-1)." (PMID 37165249, 2023). "Some NF1 associated tumours have an increased risk and prevalence in childhood such as OPGs, and others are seen more commonly in adults such as malignant peripheral nerve sheath tumours (MPNSTs), phaeochromocytomas and GISTs." (PMID 36684394, 2023). "Patients with NF1 have an increased risk of gliomas, malignant peripheral nerve sheath tumors (MPNSTs), seizures, breast cancer, and other potentially severe complications." (PMID 37959212, 2023). "Approximately 10% of benign plexiform neurofibromas progress to malignant peripheral nerve sheath tumors (MPNSTs) following loss of heterozygosity at the NF1 locus." (PMID 38201517, 2023). "Malignant schwannoma of the sciatic nerve originating in a spinal plexiform neurofibroma associated with NF-1—case report." (PMID 38013269, 2023). "Specifically, mutation in NF1 gene is associated with highly elevated risk of malignant peripheral nerve sheath tumors (MPNST), rhabdomyosarcoma, and primary brain tumors." (PMID 35320498, 2022). "Although MPNST was the predominant sarcoma associated with NF1 in our study, non-neurogenic sarcomas were also more prevalent in the NF1 group than in the general population." (PMID 33734413, 2021). "Patients with germline neurofibromatosis type 1 (NF1) microdeletions frequently exhibit hereditary syndromes such as cardiovascular anomalies and have an increased risk of malignant peripheral nerve sheath tumors (MPNSTs)." (PMID 34692515, 2021). "Subjects with NF1 have an increased oncogenic risk, including juvenile myelomonocytic leukemia, rhabdomyosarcoma, malignant peripheral nerve sheath tumor and non-invasive pilocytic astrocytoma, particularly OPG." (PMID 35096710, 2021). "Several additional proteases have been implicated in NF1 and malignant peripheral nerve sheath tumors (MPNSTs), two neuro-cutaneous syndromes that share features with NF2." (PMID 32848608, 2020). "The most common cause of early death in NF-1 patients is malignant peripheral nerve sheath tumors (MPNST) which most often occur in preexisting PNFs." (PMID 29849532, 2018).
malignant peripheral nerve sheath tumor (continued). "Germline and somatic inactivation of NF1 is associated with malignant peripheral nerve sheath tumors and gastrointestinal stromal tumors in individuals with neurofibromatosis type 140,41." (PMID 30018380, 2018). "Neurofibromatosis type 1 (NF1) is a risk factor for the development of malignant peripheral nerve sheath tumors (MPNST), which are associated with poor prognosis due to high recurrence and early metastases." (PMID 30055648, 2018). "Neurofibromatosis-1 (NF1) is an inherited disease characterised by multiple neurofibromas in which there is an increased risk of malignant transformation to malignant peripheral nerve sheath tumours (MPNSTs)." (PMID 28589254, 2017). "JQ1 has also been shown to decrease proliferation and induce apoptosis in NF1-associated malignant peripheral nerve sheath tumors." (PMID 26830473, 2016). "Neurofibromatosis type 1 (NF1) has been associated with an increased risk for development of malignancy, especially malignant peripheral nerve sheath tumors." (PMID 24876981, 2014). "PNFs have a high risk of malignant transformation into malignant peripheral nerve sheath tumors (MPNST) which is the leading cause of NF1-related death." (PMID 25340526, 2014). "Neurofibromatosis type-1 (NF1), resulting from NF1 gene loss of function, is characterized by an increased risk of developing benign and malignant peripheral nerve sheath tumors (MPNSTs)." (PMID 23244685, 2012). "Intraoral neurofibromas associated with NF-1 are quite common, but the occurrence of malignant peripheral nerve sheath tumor (MPNST) in the oral cavity is very rare." (PMID 21731277, 2011). "Persons with NF-1 are at increased risk for malignant conditions, especially malignant peripheral nerve sheath tumor (MPNST), leukemia and rhabdomyosarcoma." (PMID 20219130, 2010). "Germline deletions of NF1 are frequently associated (∼50%) with another sarcoma, malignant peripheral nerve sheath tumors (MPNST), through its association with neurofibromatosis-1." (PMID 18784837, 2008). "However, NF1 mutations were identified in only eight patients—five malignant peripheral nerve sheath tumor (MPNST), two RMS (epithelioid and pleomorphic), and one UPS." (PMID 40911493, 2025). "However, long-term follow-up is essential due to the risk of recurrence or development of other NF1-associated tumors, such as malignant peripheral nerve sheath tumors or gastrointestinal stromal tumors." (PMID 40741550, 2025). "Recently, large-scale tumor sequencing efforts have demonstrated NF1 as one of the most frequently mutated genes in human cancer, being mutated in approximately 5–10% of all tumors, especially in malignant peripheral nerve sheath tumors and different skin tumors." (PMID 37627552, 2023). "Importantly, no patient (despite 17 individuals being included who were over 20 years of age) was diagnosed with a malignant peripheral nerve sheath tumour or other NF1-associated malignancy." (PMID 34897289, 2022). "Interestingly, a previously published study demonstrated that cotargeting of BRD4 and MAPK signaling promoted cell death in a NF1 loss-of-function mouse model of malignant peripheral nerve sheath tumor (MPNST)." (PMID 32960816, 2020). "EVI2B enhanced the migration of NF1-associated malignant peripheral nerve sheath tumors." (PMID 32426282, 2020). "PET-CT might have some utility in diagnosing neurofibromatosis 1 (NF1) associated malignant peripheral nerve sheath tumours (MPNST)." (PMID 27891213, 2016). "We also identified STAT3 as a common point of convergence for many receptor tyrosine kinases involved in the angiogenic response within Neurofibromatosis 1 (NF1) associated malignant peripheral nerve sheath tumours (MPNSTs), reflecting the wider implications of this work." (PMID 26697523, 2015).
malignant peripheral nerve sheath tumor (continued). "Circulating miR-24 is elevated in patients with breast cancer, lung cancer, malignant peripheral nerve sheath tumor with the NF1 mutation, multiple system atrophy, osteoporotic fracture, Parkinson's disease, preeclamptic pregnancy, rheumatoid arthritis and type 1 diabetes." (PMID 25364765, 2014). "From a clinical point of view, the molecular diagnosis of a large NF1 deletion is important because they are frequently associated with severe clinical manifestations including an increased risk of malignant peripheral nerve sheath tumors (MPNSTs) as compared with the general NF1 population." (PMID 22151963, 2011). "Besides, NF1 is associated with various malignant tumors such as malignant schwannoma (neurofibrosarcoma), medulloblastoma, astrocytoma and pheochromocytoma." (PMID 16961930, 2006). "In particular, NF1 is associated with the development of malignant peripheral nerve sheath tumors (MPNST) at an early age and with a 1000-fold higher risk compared to the general population." (PMID 40585258, 2025). "NF-1 associated malignant peripheral nerve sheath tumors (MPNST)—Delucravatinib associated with Mirdametinib, a MEK-inhibitor, showed an inhibitory effect on cell proliferation and induced apoptosis in vitro." (PMID 41463071, 2025). "For instance, malignant peripheral nerve sheath tumors (MPNST) are characterized by mutations in the NF1 tumor suppressor gene (50%)." (PMID 35626152, 2022). "There are evidences that biallelic SUZ12 loss promotes malignant peripheral nerve sheath tumor (MPNST) progression in NF1." (PMID 31652930, 2019). "Moreover, JQ1 treatment has shown synergistic activity with trametinib in malignant peripheral nerve sheath tumors (MPNSTs) driven by neurofibromin 1 (NF1) mutation and polycomb repressive complex 2 (PRC2) loss, suggesting further utility of this therapeutic approach in other tumor types." (PMID 30353166, 2019). "In sharp contrast, around 5%–10% of NF1 patients have a large deletion encompassing the NF1 gene, which is associated with a high number of cNF and an increased risk for malignant peripheral nerve sheath tumor (MPNST)." (PMID 29987131, 2018). "It has been speculated that the mutation of tumor suppressor NF-1 gene increases the patient's risk for the development of various malignancies mainly derived from the neural crest such as malignant schwannoma, neurofibrosarcoma, intracranial glioma, and pheochromocytoma." (PMID 23533906, 2013). "There are strong associations with certain inherited genetic conditions, such as a 10% lifetime risk of malignant peripheral nerve sheath tumour (MPNST) in individuals with familial neurofibromatosis, caused by mutations in the NF1 gene." (PMID 38734790, 2025). "The most fatal clinical manifestation of NF1 is a malignant peripheral nerve sheath tumor (MPNST), which involves the malignant transformation of preexisting neurofibromas." (PMID 40002695, 2025). "In NF1 mutant malignant peripheral nerve sheath tumor (MPNST) models, SHP2 inhibition transiently reduced tumor size, and combining it with further MAPK pathway inhibition increased durability." (PMID 40992926, 2025). "Patients with a germline variant in NF1, have a lifelong increased risk of GIST as well as malignant peripheral nerve sheath tumour (MPNST)." (PMID 38840030, 2025). "Malignant Peripheral Nerve Sheath Tumors (MPNSTs) are rare, aggressive soft tissue sarcomas, which most often occur as a neoplasm in patients with neurofibromatosis 1 (NF1)." (PMID 38895115, 2024).